PDPN (podoplanin)
Diseases named in the same sentence as PDPN in open-access papers (continued):
Sharing a sentence is not in itself a finding about the gene and the disease.
tumor (continued). "An explanation for the oncogenic behavior of podoplanin came from proteomic studies in which upregulation of pro-oncogenic proteins and downregulation of tumor suppressors was observed in MDCK cells overexpressing human podoplanin." (PMID 30736372, 2019). "The EMT process is controlled and enhanced by various transcription factors depending on the skin tumor (such as Zeb, Twist, Snail families, and podoplanin), expressed not only by cancer cells but also within the tumor microenvironment." (PMID 31934531, 2019). "Tumor cells were also stained in the sections of spermatogonia, suggesting that PDPN was expressed in normal cells of spermatogonia." (PMID 29976954, 2018). "Meanwhile, the tumor cell-induced platelet aggregating effect of the podoplanin CLEC-2 interplay was revealed in several animal models and different antibodies targeting different epitopes were generated." (PMID 30305116, 2018). "Changes in mesothelin, calretinin and podoplanin gene expression levels were also evaluated in tumor samples." (PMID 29527515, 2018). "The blocking podoplanin–CLEC-2 interaction by neutralizing antibody contributes to suppress the tumor cell growth." (PMID 30279963, 2018). "Ki-67 staining demonstrated in situ proliferative potential of Il7-expressing PDPN+ CAFs suggesting that the cells are engaged in dynamic cellular interactions in the tumor margin." (PMID 29632733, 2018). "The PDPN induces the formation of membrane-actin structures and promotes tumor cell invasion via plasma membrane extensions." (PMID 29765527, 2018). "Moesin is a member of the ERM (ezrin, radixin and moesin) proteins that participate in cell migration and tumor invasion through transductional signals sent to actin filaments by glycoproteins, such as podoplanin." (PMID 29310601, 2018). "In this study, the ratio of podoplanin-positive/EpCAM-positive CTCs showed an independent prognostic value with respect to the type of treatment and tumour staging." (PMID 29890622, 2018). "Fibroblasts expressing TGM2 were observed throughout the tumour stroma, while the expression of PDPN and TNC is lower and more restricted." (PMID 29551776, 2018). "The prognostic value of PDPN-expressing mesenchymal cells in the tumor microenvironment remains to be further studied." (PMID 30592710, 2018). "Podoplanin induced an epithelial to mesenchymal transition (EMT) in MDCK cells, increased cell migration, and was associated with tumor invasion." (PMID 30305116, 2018). "PDPN expression in circulating tumor cells was also considered as a poor prognostic factor in patients with locally advanced or metastatic HNSCC." (PMID 30002682, 2018). "A high expression of PDPN was an independent risk factor for DSS (relative risk (RR) = 2.153, p = 0.022) and tumor size >20 mm was an independent risk factor for both DFS (RR = 2.514, p = 0.013) and DSS (RR = 2.535, p = 0.032)." (PMID 28702871, 2018). "GCV-treated PDPN-tk mice revealed significantly suppressed lymphangiogenesis in both tumor center and tumor margin/periphery, defined as 100 μm from the tumor edge, while angiogenesis was not significantly altered." (PMID 30592710, 2018). "Supporting this, tumour-derived MPs that bear podoplanin have been detected in the blood of patients with pancreatic and colorectal cancer." (PMID 30314362, 2018). "In previous studies, BMI and PDPN were found to be expressed in the majority of HNSCC tumor samples, especially at the invasive front." (PMID 30002682, 2018). "Based on the expression of podoplanin (PDPN), a marker for MPM tumor cells, ascites fluids contained slightly more PDPN+ tumor cells compared to pleural fluids (median 0.5% vs 0.1%)." (PMID 29163783, 2017). "More analyses using podoplanin-positive tumor cells and tumor/metastasis model containing the patient-derived model are required to provide insights into the development of new therapies targeting the podoplanin–CLEC-2 interaction." (PMID 28674748, 2017).
tumor (continued). "Podoplanin is expressed on various tumor cells, including squamous cell carcinomas (SCCs), glioblastoma, osteosarcoma, bladder carcinoma, mesothelioma, and seminoma, and its expression correlates with poor prognosis in brain and lung tumors." (PMID 28674748, 2017). "Using IF, we analyzed the co-localization of PDPN-positive CAFs with blood vessels stained with antibody directed against CD34 in tumor stroma of IDC samples." (PMID 28938000, 2017). "To evaluate the significance of podoplanin in TGF-β release from tumour cell-platelet reactants, we established two UM-UC-5 cell lines in which podoplanin was knocked down, UM-UC-5/shPDPN_23 and UM-UC-5/shPDPN_26." (PMID 28176852, 2017). "PD-1 ligand-1, PD-L1, expression was detected on DCs, B cells, macrophages and PDPN+ MPM tumor cells in all ascites samples, while in pleural samples PD-L1 expression varied per cell type." (PMID 29163783, 2017). "In summary, our findings suggest that podoplanin-dependent platelet aggregation promotes tumour embolization and extravasation via EMT induction by TGF-β release from platelets." (PMID 28176852, 2017). "On the other hand, Podoplanin is expressed primarily in the cytoplasm as well as on the plasma membrane of the tumour cells." (PMID 28912668, 2017). "This implies mobilization from the tumor primary site in which they interact with CAFs which are overexpressing podoplanin." (PMID 28416768, 2017). "Second, using immunofluorescence, the co-localization of PDPN-positive CAFs with blood vessels stained with antibody directed against CD34 was observed in tumor stroma of IDC samples." (PMID 28938000, 2017). "The percentage of CD4+ T cells present in the effusions is significantly correlated with response to chemotherapy, while the percentage of PD-L1+ PDPN+ tumor cells can be translated as a significant prognostic factor for worse outcome." (PMID 29163783, 2017). "To elucidate the role of podoplanin-mediated tumour-induced platelet aggregation in tumour behaviour, we first investigated podoplanin-positive tumour cell lines for potential to induce platelet aggregation." (PMID 28176852, 2017). "This confirms the anti-adhesive effect of podoplanin in the tumor microenvironment and its role in favoring CCR7+ carcinoma cell movement and mediating escape." (PMID 28416768, 2017). "This work demonstrates that tumor hypoxia, by modulating the expression of molecules such as PDPN, leads to easier liberation of tumor cells and, lowering the NK cells recruitment upon CCL21 presentation, it impairs the anti-tumor immune defence." (PMID 28416768, 2017). "An other potential mechanism for tumour cell invasion and metastasis is the podoplanin-mediated remodelling of actin cytoskeleton and tumour invasion, also described in NSCLC." (PMID 28771186, 2017). "For example, podoplanin is a potent platelet agonist and has been shown to be upregulated in several types of tumours." (PMID 28737696, 2017). "In accordance with this, the present study revealed that such podoplanin-mediated effects can influence the pathological state of the angiogenesis in the tumor site." (PMID 28938000, 2017). "Scattered PDPN expressions were occasionally detected in cytoplasm or membrane in tumor cells outside the basolateral layer of cancer nests in some cases." (PMID 28086225, 2017). "The fact that PD-L1 expression on PDPN+ tumor cells was found to be a significant factor in our small cohort supports the need for further research in a larger cohort." (PMID 29163783, 2017). "To confirm that mechanism by which platelets promoted metastasis through TGF-β release and EMT induction in podoplanin-positive epithelial tumours extended to other tumour, we analysed patient-derived lung SCC cell lines expressing podoplanin." (PMID 28176852, 2017). "Real-time quantitative PCR (RTQ–PCR) was used to check the expression levels of LYVE–1, VEGFR–3, Podoplanin, and Prox–1 in tumor and para-cancerous tissues." (PMID 29162097, 2017).
tumor (continued). "Based on flow cytometric PDPN staining we found only few circulating PDPN+ tumor cells were present in ascites samples and even less were found in pleural fluids." (PMID 29163783, 2017). "Highest PD-L1 expression was found on the PDPN+ tumor cells in both fluid types, with a median expression of 19.4% PD-L1+ cells and a range of 20 up to 14524 on a per cell basis." (PMID 29163783, 2017). "On the other hand, when the podoplanin expression was low in peripheral stroma, there was also low podoplanin expression in tumor stroma." (PMID 28938000, 2017). "Previously, we reported that a humanized chimeric anti-podoplanin antibody, ChMS-1 suppressed PC-10 tumour growth by independent antibody effector activity." (PMID 28642617, 2017). "They found tumor cells in those cell blocks based on cytology, confirming our data about the presence of PDPN+ tumor cells in the fluid samples." (PMID 29163783, 2017). "Our data show that expression of PD-L1 on PDPN+ tumor cells in our fluid samples is a poor prognostic factor." (PMID 29163783, 2017). "Some anti-podoplanin mAb requires ADCC/CDC activities for suppression of tumor growth and metastasis." (PMID 28674748, 2017). "One of the best characterised mechanisms of tumour cell-induced platelet activation is through podoplanin/CLEC-2 interaction." (PMID 28737696, 2017). "Podoplanin-expressed lymph node stromal cells enhance tumor growth in vivo by eliminating CD4+ tumor-infiltrating lymphocytes that limit the efficiency of tumor immunotherapy." (PMID 28674748, 2017). "In accordance with this, the present study revealed for the first time, that such podoplanin-mediated effects can affect tube formation by endothelial cells and participate in their pathological properties in the tumor context." (PMID 28938000, 2017). "Other mechanisms of cancer-dependent platelet activation that involve cell-to-cell contact include the overexpression of podoplanin, a trans-membrane protein (also known as “aggrus”) that is expressed in several tumor types." (PMID 28894697, 2017). "Positivity of PD-L1 on DCs was found in all samples, while positivity of PD-L1 on B cells was found in nine samples and ten samples showed expression of PD-L1 on macrophages and PDPN+ tumor cells." (PMID 29163783, 2017). "In the present study, we clearly demonstrated that podoplanin-positive tumour cells acquired high invasive ability through EMT induction following TGF-β release from activated platelets." (PMID 28176852, 2017). "In this study, we found that podoplanin-positive tumour cells induced platelet aggregation and that growth factors and cytokines were released during platelet aggregation through the podoplanin–platelet interaction." (PMID 28176852, 2017). "High level of podoplanin expression was observed in the vicinity of numerous blood vessels present in tumor stroma, and weak staining with antibody directed against PDPN was found in the proximity of single blood vessels." (PMID 28938000, 2017). "The positive expression rates of LYVE–1, VEGFR–3, Podoplanin, and Prox–1 in tumor tissues were 100, 93.6, 100, and 91.4%, but 100, 100, 100, and 87.2% in para-cancerous tissues." (PMID 29162097, 2017). "Very little is known about the role of podoplanin expressed by CAFs, its biological properties or its function as a tumor promoter." (PMID 28938000, 2017). "Treatment with an antiplatelet agent or podoplanin-neutralizing antibody depressed the growth of an LSCC tumour xenograft via suppression of EGFR phosphorylation." (PMID 28642617, 2017). "Comparison of the protein profiles of MDCK cells following PDPN expression reveals extensive reprogramming in whole cells and EXOs associated with EMT and tumor progression." (PMID 26893367, 2016). "Podoplanin-mediated platelet aggregation enhances tumor growth and metastasis by secreting growth factors and by forming tumor emboli in the microvasculature." (PMID 26684030, 2016).
tumor (continued). "We have previously identified a type-I transmembrane sialoglycoprotein, podoplanin, also known as Aggrus, as a platelet aggregation-inducing factor in highly metastatic tumor cells." (PMID 26684030, 2016). "A recent findings showed that podoplanin assisted lung tumor cells with local invasion; that is tumor cells invaded by following the podoplanin-positive CAFs into surrounding extracellular matrix through RhoA activation." (PMID 27996035, 2016). "Our results suggest the requirement of simultaneous inhibition of PLAG3/4 for complete suppression of podoplanin-mediated tumor growth and metastasis." (PMID 26684030, 2016). "PDPN-mediated platelet aggregation via CLEC-2 interaction facilitates tumor cell growth and pulmonary metastasis, whereas, in normal cells, this interaction is relevant for development of the lymphatic vasculature, lymphangiogenesis and the immune response." (PMID 26893367, 2016). "Recently, we and others have found that PDPN is a component of ventral membrane protrusions called invadopodia that mediate degradation of the extracellular matrix (ECM) by tumor cells." (PMID 26893367, 2016). "Taking all these findings together, palladin was much more specific and better for use as an IHC marker of CAF, although both α-SMA and podoplanin also showed some dependency on tumor cells." (PMID 27023252, 2016). "Taken together, these results indicate that PDPN stimulates EV biogenesis according to tumor progression." (PMID 26893367, 2016). "Podoplanin-induced pulmonary metastasis was significantly blocked by a single administration of PG4D1 or PG4D2 mAb on the day before tumor inoculation, like MS-1 mAb." (PMID 26684030, 2016). "Of note, antibodies and lectins targeting PDPN halt the growth and dissemination of PDPN-expressing tumor cells." (PMID 26893367, 2016). "This interaction seems to be crucial for tethering tumor cells to hyaluronan-rich ECMs and for PDPN stimulation of directional migration." (PMID 26893367, 2016). "We decided to use EvG staining and podoplanin immunostaining because the former illustrates the blood vessels and clarifies vascular destruction by tumor cells." (PMID 25884820, 2015). "For example, antibodies against PDPN can inhibit the growth and metastasis of tumor cells that express PDPN in mice." (PMID 25826087, 2015). "This was based on the findings that C6/Lung cells expressed high levels of PDPN and induced platelet aggregation and the formation of tumor cell-platelet aggregates." (PMID 26528756, 2015). "Podoplanin was expressed in the microvascular structures and the cytoplasm of tumor cells, with podoplanin-positive microvascular structures clearly detected in the peritumoral stroma and connective tissue." (PMID 26622791, 2015). "The present study showed that the expression of podoplanin was clearly distributed in the peritumoral stroma and cytoplasm of tumor cells." (PMID 26622791, 2015). "The tumor volume resulting from co-injection with CAFs-Ctrl was larger than the tumor volume resulting from co-injection with CAFs-PDPN at 4 weeks (mean tumor volume: CAFs-PDPN, 757.1 mm3 vs. CAFs-Ctrl, 1469 mm3); however, the difference was not significant." (PMID 25909164, 2015). "The metastatic potency of cancer and the frequency of tumor cells embolized in the microvasculature of the lung are correlated with the platelet aggregation activity of PDPN." (PMID 26528756, 2015). "PDPN is activated by endogenous lectins that bind to these extracellular carbohydrate moieties to induce tumor cell motility and metastasis." (PMID 25826087, 2015). "We also examined the frequency of Geminin-positive cancer cells of invasive lung adenocarcinoma with a tumor size of 2–3 cm in diameter (Cases with PDPN-positive CAFs vs Cases with PDPN-negative CAFs, n = 20, each)." (PMID 25909164, 2015). "This indicates that PDPN-induced platelet-tumor cell interaction is a potential target for the development of an anti-metastases regimen." (PMID 26528756, 2015).
tumor (continued). "Together with previous data, these results demonstrate the involvement of podoplanin in two key features of aggressive tumours: increased directed cell motility and efficient remodelling of the ECM." (PMID 25486435, 2015). "The Src tyrosine kinase utilizes the focal adhesion adaptor protein Cas/BCAR to induce PDPN expression in order to promote tumor cell motility." (PMID 25826087, 2015). "In fact, MASL, which has a high affinity for O-linked carbohydrate chains containing sialic acid, targets PDPN in order to inhibit tumor cell growth and motility at nanomolar concentrations." (PMID 25826087, 2015). "Strong podoplanin expression was significantly correlated with tumor status (P=0.001), venous invasion (P=0.035) and UICC stage (P=0.029)." (PMID 26095281, 2015). "Tumor angiogenesis and lymphangiogenesis were examined by staining primary tumor sections with the panendothelial cell marker endomucin and the lymphatic specific marker podoplanin." (PMID 25924234, 2015). "Previous studies indicate that antibodies and lectins can be used to target PDPN in order to inhibit tumor cell migration and growth." (PMID 25826087, 2015). "Podoplanin (PDPN) enhances tumor metastases by eliciting tumor cell-induced platelet aggregation (TCIPA) through activation of platelet C-type lectin-like receptor 2 (CLEC-2)." (PMID 26528756, 2015). "Podoplanin is expressed on the surface of tumor cells and induces platelet aggregation by binding to CLEC-2, facilitating hematogenous tumor metastasis." (PMID 26418160, 2015). "The PDPN function we reveal is consistent with the majority of previous reports linking increased expression of podoplanin with tumor progression." (PMID 24797369, 2014). "Various intensity of PDPN labeling (from moderate to strong) was observed in the cytoplasm of tumor cells and in the most of cases, staining was distributed uniformly across the cancer." (PMID 24797369, 2014). "Our findings cannot directly link the PDPN expression in PTC tumor cells with metastatic tendency in papillary cancer, mainly due to the lack of information regarding lymph node involvement." (PMID 24797369, 2014). "Recent findings prove that podoplanin is important to drive directional cell migration in epithelial and tumor cells." (PMID 25480364, 2014). "A number of previous in vitro and in vivo studies have shown that PDPN is involved in cell motility and tumour invasion and metastasis." (PMID 24527067, 2014). "It is likely that the upregulated expression of PDPN has a role in the processes of tumour proliferation and invasion." (PMID 24527067, 2014). "As assessed by podoplanin immunodetection on tumor sections and its quantification through a computerized method, the intratumoral lymphatic vessel density was increased in the presence of BM-MSC." (PMID 25222747, 2014). "The expression of PDPN mRNA was up-regulated in ∼70% of the analyzed tumor samples (by at least 2-fold) compared to paired normal thyroid tissues." (PMID 24797369, 2014). "For that reason, we further characterized the serosal tumors by immunofluorescence (IF) for vimentin, cytokeratin and podoplanin in at least one tumor from each affected mouse." (PMID 24405760, 2014). "Podoplanin is also considered to be involved in the process of tumor cell migration, invasion, and metastasis." (PMID 24804195, 2014). "The podoplanin expression of CAFs positively correlated with the VEGF-C expression of the tumor cell and the intratumoral amount of CD31+ blood vessels." (PMID 25254213, 2014). "Numerous fibroblasts were observed in the area of cancerous invasion, and PDPN+ fibroblasts were observed close to the tumor cells." (PMID 24354864, 2013). "Data on lymphangiogenesis evaluated by anti-podoplanin immunostaining were available from previous studies, platelets within the tumor tissue were assessed by CD61 immunostaining." (PMID 23840559, 2013).